LGALS9C (galectin 9C)
Description:
Binds galactosides.
Synonyms: Gal-9C
Tractability: PROTAC: ubiquitination databases record sites on it.
Target class: Other cytosolic protein
Gene: Protein-coding gene on chromosome 17 (18,476,737 to 18,494,945, forward strand). Ensembl gene ENSG00000171916.
Subcellular location (Human Protein Atlas): Cytosol
Gene Ontology:
Molecular function: protein binding; carbohydrate binding; galactoside binding; receptor ligand activity
Biological process: negative regulation of CD4-positive, alpha-beta T cell proliferation; negative regulation of type II interferon production; positive regulation of gene expression; negative regulation of alpha-beta T cell activation; positive regulation of immune response; positive regulation of mononuclear cell migration; regulation of innate immune response; regulation of T cell apoptotic process; regulation of T cell proliferation; signal transduction
Cellular component: cytosol; nucleus
Genetic constraint (gnomAD): Loss-of-function variants: 6 observed, 21.45 expected, observed/expected ratio (o/e) 0.28, 90% interval 0.15 to 0.55. The synonymous counts are far from expectation, so gnomAD's model fits this gene poorly and the ratio says little. Missense variants: 92 observed, 262.32 expected, observed/expected ratio (o/e) 0.35, 90% interval 0.29 to 0.42. Synonymous variants: 42 observed, 90.57 expected, observed/expected ratio (o/e) 0.46, 90% interval 0.36 to 0.6.
Homologues: Orthologues: chimpanzee LGALS9C (95% identical), dog LGALS9 (67% identical), Caenorhabditis elegans lec-12 (28% identical), Caenorhabditis elegans lec-3 (28% identical), Caenorhabditis elegans F40H6.5 (27% identical), Caenorhabditis elegans lec-1 (27% identical), Drosophila melanogaster galectin (26% identical), Drosophila melanogaster CG11374 (21% identical), zebrafish lgals3b (20% identical), Caenorhabditis elegans C27C7.5 (20% identical), Drosophila melanogaster CG13950 (17% identical), Caenorhabditis elegans lec-6 (15% identical), and 13 more. Paralogues in human: LGALS9B (99% identical), LGALS9 (94% identical), LGALS4 (36% identical), LGALS8 (31% identical), LGALS12 (27% identical), LGALS3 (22% identical), LGALSL (16% identical), LGALS7 (15% identical), LGALS7B (15% identical), LGALS1 (13% identical), GRIFIN (10% identical), LGALS2 (10% identical), and 4 more.
Diseases named in the same sentence as LGALS9C in open-access papers:
LGALS9C is named in the same sentence as 2 diseases in open-access papers, as found by Europe PMC text mining. Sharing a sentence is not in itself a finding about the gene and the disease. The quoted sentences say what the papers report.
diabetes (1 paper, 2023). "LGALS9C, located in 17p11.2, is involved in cytoplasmic intracellular functions, and controls AMP-activated protein kinase in response to lysosomal damage, which is caused by diabetes, immune responses, and obesity." (PMID 36979105, 2023).
LGALS9C also shares sentences with these, for which no sentence is quoted: Obesity (1 paper).